GZMA (granzyme A)
Diseases named in the same sentence as GZMA in open-access papers (continued):
Sharing a sentence is not in itself a finding about the gene and the disease.
Sepsis (16 papers, 2016 to 2026). Sepsis is defined as life-threatening organ dysfunction caused by a dysregulated host response to infection. "The analysis of survival showed that despite the fact that GzmA-/- and GzmK-/- mice showed a similar loss of weigh and sepsis score, only GzmA deficient mice showed a significant increase in survival compared with WT mice." (PMID 34815792, 2021). "In conclusion, using GzmA deficient mice and direct inactivation of GzmA, we have demonstrated that extracellular GzmA plays an important role in sepsis pathogenesis." (PMID 33664861, 2021). "During sepsis induced by a commensal strain of E. coli isolated from blood of a mice suffering from sepsis induced by CLP, a lower sign of sepsis was observed in GzmA or GzmK deficient mice, when a murine sepsis score was applied, compared to WT mice." (PMID 34815792, 2021). "Although the impact of GzmK absence in E. coli sepsis seems to be less pronounced than that of GzmA absence, GzmK deficient mice have shown significantly lower levels of IL-1β in serum compared with WT mice." (PMID 34815792, 2021). "The relevance of these findings was supported by the observation that GzmA deficient mice were resistant to CLP as well as to E. coli-induced sepsis." (PMID 33664861, 2021). "Sepsis was induced in WT, GzmA and GzmK deficient mice by i.p. administration of 2×108 CF U/mL of an E. coli strain isolated from blood of mice suffering from CLP-induced sepsis." (PMID 34815792, 2021). "Our study thus adds to previous literature and confirms that GzmA is a key mediator of sepsis associated with different bacterial pathogens." (PMID 33664861, 2021). "GzmA deficiency has been shown to protect against LPS-induced endotoxicosis as well as against sepsis induced by different bacterial pathogens including gram negative Brucella microti or gram positive Streptococcus pneumoniae." (PMID 32655547, 2020). "Therefore, GzmA−/− mice or mice treated with GzmA inhibitors escape from lethal inflammatory outcomes during acute bacterial infections, causing sepsis or lipopolysaccharide (LPS)-induced peritonitis, leading to systemic inflammation." (PMID 41009359, 2025). "However, GzmA and GzmK deficient mice showed a lower sepsis score in comparison with WT mice, although only GzmA deficient mice exhibited increased survival." (PMID 34815792, 2021). "Indeed, most cytokines are reduced in GzmA deficient mice suffering from sepsis." (PMID 32655547, 2020). "These exploratory findings are consistent with experimental models and support further evaluations of extracellular GzmA to investigate its biological and potential translational relevance in sepsis." (PMID 42292430, 2026). "Cytotoxic T cells contribute as an important source of GzmA and GzmB during bacterial infections and sepsis, along with NK cells." (PMID 41009359, 2025). "Compared to bacteraemic NK cells, sepsis NK cells maintained a level of cytotoxicity gene expression, including GZMA and PRF1 (1.03log2FC & 0.53log2FC)." (PMID 41208955, 2025). "In this line, reduced levels of pro-inflammatory cytokines were found in gzmA knockout mouse models of rheumatoid arthritis and sepsis." (PMID 36362341, 2022). "Our data also suggest that inflammation induced by GzmA plays a critical role in the development of sepsis during peritonitis." (PMID 33664861, 2021). "Intracellular expression of GzmA and GzmK was analysed in different immune spleen cell subsets 18 h after sepsis induction." (PMID 34815792, 2021). "In order to understand the role of GzmK in the dysregulation of the inflammatory response in sepsis and the potential use of GzmA and/or GzmK as therapeutic targets in sepsis, it is critical to clarify the relative role of these Gzms in this pathology." (PMID 34815792, 2021). "To confirm the role of GZMA in peritoneal sepsis we employed E. coli-induced sepsis as additional model." (PMID 33664861, 2021).
Sepsis (continued). "Once we confirmed that the absence of GzmA increases the survival of mice during abdominal CLP-induced sepsis, correlating with a reduced inflammatory response that did not compromise bacterial control, we decided to establish the cellular source of GzmA." (PMID 33664861, 2021). "Pending of validating the clinical significance of the presence of soluble Gzms in septic patients, studies in animal models in vivo indicate a key role for some Gzms like GzmA and GzmM in inflammation and sepsis." (PMID 32655547, 2020). "Regarding the clinical utility of Gzms in sepsis prognosis, it was found that increased levels of GzmA and GzmB in CD8+T cells were associated with a worse prognosis in severe sepsis patients." (PMID 32655547, 2020). "For instance, a study showed that there was low level of GzmA in peritoneal lavage fluid of healthy mice while this level increased overtime during sepsis induced by E. coli." (PMID 32655547, 2020). "HIV positive sepsis patients in both ICU cohorts showed overexpression of genes involved in granzyme signaling (GZMA, GZMB), cytotoxic T-cell signaling (CD8A, CD8B) and T-cell inhibitory signaling (LAG3), compared to HIV negative patients." (PMID 26871709, 2016). "Differential expression analysis of sepsis NK cells highlighted further immunosuppression through the downregulation of critical genes involved in target cell killing such as granzyme A (GZMA), lectin response, as well as antigen processing and presentation pathways compared to controls." (PMID 41208955, 2025). "An important aspect to answer this question is the cell source of GzmA during sepsis." (PMID 33664861, 2021). "In addition, our results employing an inhibitor of extracellular GzmA, serpinb6b, in vitro and in vivo, strongly suggest that GzmA enhances the inflammatory pathological response in sepsis in the extracellular space." (PMID 33664861, 2021). "Therefore, supporting our findings it is possible that in sepsis, as natural GzmA inhibitors decrease, the active fractions of this protease in the bloodstream increase, explaining why extracellular GzmA remains active during sepsis." (PMID 33664861, 2021). "Subsequently we analysed the cell source of GzmA and GzmK during sepsis induced by E. coli." (PMID 34815792, 2021). "Thus, the role of GzmK, in comparison with its closest homologue GzmA, in sepsis has been analysed using a mouse model of bacterial sepsis induced by the bacteria E. coli, one of the most common pathogens involved in human sepsis." (PMID 34815792, 2021). "However, at 48 h of sepsis induction, GzmA-/- and GzmK-/- mice showed a slight but significant lower sepsis score compared with WT mice." (PMID 34815792, 2021). "However, GzmA seems to play a more relevant role in this pathology and targeting GzmA seems to be sufficient to reduce inflammation and increase survival in sepsis." (PMID 34815792, 2021). "Indeed, our results show that therapeutical inhibition of active GzmA with serpinb6b similarly increased survival in WT and GzmK -/- mice and reduced IL-6 serum levels, confirming the potential of GzmA as a therapeutic target for sepsis treatment." (PMID 34815792, 2021). "In contrast to PARs deficient mice, GzmA deficient mice are protected from endotoxemia and sepsis and, thus, PAR1 and 2 should not play an important role in GzmA-induced inflammation during sepsis." (PMID 32655547, 2020). "It seems that in light of the different results pointing to a complex regulation of PARs during sepsis, the involvement of PARs in the detrimental effects of GzmA on vascular permeability during sepsis will require further clarification and specific experimental validation." (PMID 32655547, 2020). "Since some Gzms like GzmA and GzmM seem to be inflammatory mediators responsible of the detrimental effects of LPS in sepsis, including TNF-α production, they also could contribute to altered endothelial permeability." (PMID 32655547, 2020).
Sepsis (continued). "Recent studies have found that GzmA, GzmB, GzmK, and GzmM act as pro-inflammatory mediators and could be involved in the pathophysiology of sepsis." (PMID 32655547, 2020). "Indeed, studies in animal models indicate that GzmA is involved in the cytokine release syndrome characteristic of sepsis." (PMID 32655547, 2020). "Thus, in this study we focused on sepsis patients to determine levels of excreted Granzyme A (GrA) as well as HBP in plasma and AKI." (PMID 33088624, 2020). "PARs are expressed by a variety of cells and the function in each cell type might differ, which would explain the differences between the in vitro and the in vivo observations regarding PAR-1, GzmA, and sepsis." (PMID 32655547, 2020). "This system consists of a capture antibody against GzmA followedby incubation with probe-1, which presents a high specificity to determinethe enzymatic activity of GzmA, as validated using pure proteasesand samples from GzmAKO mice suffering from different inflammatorydiseases like sepsis and HLH." (PMID 38751645, 2024). "The immunoprobe is also able to detectextracellular GzmA activity in human samples from septic patients.Indeed, the presence of active gzmA in serum from septic patientsis significantly higher than that in HDs, confirming the potentialrole of active gzmA in sepsis." (PMID 38751645, 2024). "Recent evidence suggests that Granzyme A (GzmA), a serine protease mainly expressed by NK and T cells, could act as a proinflammatory mediator and could play an important role in the pathogenesis of sepsis." (PMID 33664861, 2021). "In addition, the biological relevance of GzmA and GzmK in sepsis has been compared." (PMID 34815792, 2021). "Taking into account that GzmA deficiency does not affect pathogen control (our own results and 5), our combined results in human and mouse models suggest that extracellular GzmA is a promising target to treat peritoneal sepsis." (PMID 33664861, 2021). "Based on these experimental evidences it could be hypothesized that by targeting GzmA, bacteria-associated sepsis could be ameliorated without compromising the ability of the immune system to control infection." (PMID 32655547, 2020). "Study showed some hub genes (CD2, CD27, GZMA, KLRB1, and PRF1) have been screened out as sepsis biomarkers and all of them were down regulated genes in sepsis, which consistent with our findings." (PMID 39654893, 2024). "Based on the discussion and analysis, it is reasonable to assume that IL7R, GZMA and CD8A possess significant potential value in the diagnosis and prediction of sepsis." (PMID 39654893, 2024). "Although the half-life of mRNA has a significant impact on protein formation, it does not affect the conclusion of the data analysis in this article that IL7R, GZMA and CD8A may serve as the attractively potential molecular biomarkers for sepsis." (PMID 39654893, 2024). "Our results show that despite both proteases contribute to bacterial sepsis, including disease progression and generation of some inflammatory cytokines in vivo, only the absence of GzmA has a relevant impact in sepsis survival." (PMID 34815792, 2021). "Regarding GzmA, this protease can also degrade some proteins of the ECM like fibronectin or collagen IV and also could be released by NK cells during sepsis, although the biological functions of these processes remain unexplored." (PMID 32655547, 2020). "In addition, these results are strengthened by a significantly lower cytotoxic module score (calculated using the AddModuleScore function in Seurat V4 using the cytotoxic-related genes GZMH, GZMK, GZMA, GZMB, PRF1, and GNLY) in all sepsis cytotoxic cell subsets compared to bacteraemia and controls." (PMID 41208955, 2025). "However, IL7R, GZMA and CD8A may serve as the attractively potential molecular biomarkers for sepsis." (PMID 39654893, 2024).
Sepsis (continued). "Thus, since serpinb6b should not affect intracellularly perforin-delivered GzmA, we suggest that GzmA does not contribute to sepsis by promoting pyroptosis 39 or other types of cell death." (PMID 33664861, 2021). "However, the role of GzmA in abdominal sepsis, the second most common form of sepsis in humans, is not known." (PMID 33664861, 2021). "Finally, we assessed whether HIV co-infection also impacts on plasma levels of circulating granzyme A and granzyme B in ICU patients with sepsis." (PMID 26871709, 2016). "However, the role of GzmA in abdominal polymicrobial sepsis had so far not been explored." (PMID 33664861, 2021). "However, the results obtained were not consistent and a clear conclusion on the role of GzmA and/or GzmB in bacterial control and sepsis could not be reached." (PMID 34815792, 2021). "In contrast, the expression of GzmA in the main T cell subsets (NKT, CD8+ T or CD4+ T cells) was very low and did not increase during sepsis." (PMID 33664861, 2021). "However, the detrimental role of GzmA in sepsis has been confirmed by several independent groups, suggesting that the in vitro function of Gzms in regulating proteins involved in coagulation might not be relevant during sepsis in vivo." (PMID 32655547, 2020). "GZMA and GZMB were under-expressed in sepsis patients without HIV infection, but not in HIV positive sepsis patients, and differences in granzyme signaling were not apparent in asymptomatic HIV patients." (PMID 26871709, 2016). "Principal component analysis of GZMA, GZMB, CD8A, CD8B, KLRD1, PRF1 and LAG3 gene expression revealed 81% explained variance for the first principal component considering HIV negative and HIV positive sepsis patients." (PMID 26871709, 2016).
viral infection (16 papers, 2010 to 2025). "All of this leads us to believe that granzyme A is an important mediator in viral infection to achieve its correct clearance." (PMID 35743021, 2022). "Elevated levels of circulating granzyme A have been detected in humans with a number of viral infections or suffering from rheumatoid arthritis." (PMID 28207896, 2017). "Knockout of GZMA in mouse models sensitizes to the animals viral infections, indicating a central role in immunity." (PMID 27123579, 2016). "We first examined the mRNA expression levels of AsEomes, IFNγ, CD8α, and granzyme A at different time intervals following bacterial and viral infection in the spleen and head kidney." (PMID 23409078, 2013). "All these data point to an important role of GzmA during the CMC response against viral infections." (PMID 31736981, 2019). "This may in part reflect a sensitivity issue, as increases in circulating granzyme K levels after viral infections can be substantially more modest than those seen for granzyme A." (PMID 28207896, 2017). "On day 3, only two pathways, granzyme A signaling and protein kinase A signaling, were enriched, suggesting a transition from an innate immune response toward a robust T cell response for clearing virus infection." (PMID 28659489, 2017). "Granzyme A deficiency has been associated with a failure to clear certain viral infections; however, feet tissue titers were not significantly affected in GzmA-/- mice (Feet)." (PMID 28207896, 2017). "The high expression of granzyme A and B in spleen could help clear virus infection, but may also involve lymphocyte injury." (PMID 21345237, 2011). "The elevated expression of certain genes (e.g. granzyme A/B) in the T cells activated through virus infection would suggest that these responding cells might be driven further along the activation/differentiation pathway than peptide stimulated T cells." (PMID 21079741, 2010). "Since viral infections can affect the cytolytic granule production and cytotoxicity of CD8+ T cells, we evaluated the intracellular expression of perforin, granzyme A and granzyme B, along with the surface expression of CD107a molecule." (PMID 39764446, 2024). "CCL5 has been shown to play a key role in the immune response to viral infection, as it is degranulated from activated HIV-specific CD8+ T cells along with perforin and granzyme A." (PMID 39119291, 2024). "In addition, GZMA from cytotoxic lymphocytes can cleave and activate GSDMB to induce pyroptosis in tumor cells as well as protect host cells during viral infection and prevent evasion from natural killer cell immunity." (PMID 37064151, 2023). "Cytotoxic effector genes (GZMA, GZMB, ID2, and PLAC8) were enriched in Δ382 SARS-CoV-2 infected patients, coupled with high plasma levels of IFN-γ, TNF-α, and IL-2 during the acute phase of virus infection." (PMID 34716845, 2022).
colorectal cancer (14 papers, 2010 to 2025). A primary or metastatic malignant neoplasm that affects the colon or rectum. "On the other hand, a recent transcriptomics analysis revealed the pro-proliferative role that extracellular GZMA plays in colorectal cancer progression." (PMID 40002821, 2025). "Consistently, recent research showed that GZMA promote the colorectal cancer progression by inducing IL-6 production through NF-κB and activating pSTAT3 in colorectal cancer." (PMID 35534879, 2022). "The expression of GZMA in CRC was positively correlated with inflammatory reaction and malignance, which suggested that GZMA was involved in the malignant progression of colorectal cancer." (PMID 35464869, 2022). "Thus, extracellular GzmA causes macrophages to release IL6 activating STAT3 in cells; and inhibiting extracellular GzmA attenuates gut inflammation, preventing colorectal cancer development." (PMID 34685542, 2021). "GzmA also correlates strongly with inflammation and colorectal cancer." (PMID 34685542, 2021). "A previous study found that coculture of eosinophils with colorectal carcinoma cells resulted in secretion of eosinophil cationic protein and granzyme A, which exerts eosinophil tumoricidal activity toward CRC cells." (PMID 28717199, 2017). "In the human colorectal cancer (CRC) cohort, SIN3B expression levels were significantly negatively correlated with CXCL9/10/11 as well as CD8A, GzmA, and GzmB." (PMID 39316363, 2024). "Granzyme A and granulysin were found to be upregulated in MSI-H colorectal cancers as compared with MSS cancers, indicating the immune mediators involved in cytotoxic lymphocyte functions are upregulated and the cells in the tumor are likely to be activated." (PMID 20631828, 2010). "scRNA-seq analysis of colorectal cancer (CRC) tissues revealed that CD8+TILs co-expressed GZMA and IFN-γ, but not other cell types." (PMID 39030523, 2024). "The results were further supported using HPA-derived protein expression data, in which GZMA was lowly expressed in 3/11 colorectal cancer samples, and not detected in 8/11 of them." (PMID 31429779, 2019).